TAB3 (TGF-beta activated kinase 1 (MAP3K7) binding protein 3)
Description:
Adapter required to activate the JNK and NF-kappa-B signaling pathways through the specific recognition of 'Lys-63'-linked polyubiquitin chains by its RanBP2-type zinc finger (NZF). Acts as an adapter linking MAP3K7/TAK1 and TRAF6 to 'Lys-63'-linked polyubiquitin chains. The RanBP2-type zinc finger (NZF) specifically recognizes Lys-63'-linked polyubiquitin chains unanchored or anchored to the substrate proteins such as RIPK1/RIP1 and RIPK2: this acts as a scaffold to organize a large signaling complex to promote autophosphorylation of MAP3K7/TAK1, and subsequent activation of I-kappa-B-kinase (IKK) core complex by MAP3K7/TAK1. [Isoform 2]: May be an oncogenic factor.
Synonyms: MAP3K7IP3; NAP1
Tractability: Antibody: its Gene Ontology location is reachable by antibodies, with high confidence. PROTAC: UniProt records ubiquitination sites on it; its protein half-life has been measured.
Gene: Protein-coding gene on chromosome X (30,827,442 to 30,975,084, reverse strand). Ensembl gene ENSG00000157625.
Subcellular location (Human Protein Atlas): Cytosol; Nuclear speckles
Pathways (Reactome):
Immune System: Alpha-protein kinase 1 signaling pathway; CLEC7A (Dectin-1) signaling; FCERI mediated NF-kB activation; IRAK2 mediated activation of TAK1 complex; IRAK2 mediated activation of TAK1 complex upon TLR7/8 or 9 stimulation; Interleukin-1 signaling; JNK (c-Jun kinases) phosphorylation and activation mediated by activated human TAK1; NOD1/2 Signaling Pathway; TAK1-dependent IKK and NF-kappa-B activation; TICAM1,TRAF6-dependent induction of TAK1 complex; TRAF6-mediated induction of TAK1 complex within TLR4 complex; activated TAK1 mediates p38 MAPK activation
Disease: SARS-CoV-2 activates/modulates innate and adaptive immune responses
Signal Transduction: TNFR1-induced NF-kappa-B signaling pathway
Gene Ontology:
Molecular function: K63-linked polyubiquitin modification-dependent protein binding; molecular adaptor activity; protein binding; zinc ion binding; ubiquitin binding
Biological process: canonical NF-kappaB signal transduction; defense response to bacterium; non-canonical NF-kappaB signal transduction; positive regulation of canonical NF-kappaB signal transduction; regulation of MAPK cascade; negative regulation of autophagy; response to bacterium
Cellular component: endoplasmic reticulum; extracellular exosome; serine/threonine protein kinase complex; cytosol; endosome membrane; plasma membrane
Homologues: Orthologues: chimpanzee TAB3 (100% identical), macaque TAB3 (99% identical), dog TAB3 (98% identical), pig TAB3 (97% identical), rabbit TAB3 (97% identical), mouse Tab3 (95% identical), rat Tab3 (92% identical), guinea pig TAB3 (91% identical), tropical clawed frog tab3 (69% identical), zebrafish tab3 (46% identical). Paralogues in human: TAB2 (39% identical), BTF3 (6% identical), BTF3L4 (6% identical).
Diseases named in the same sentence as TAB3 in open-access papers:
TAB3 is named in the same sentence as 25 diseases in open-access papers, as found by Europe PMC text mining. Sharing a sentence is not in itself a finding about the gene and the disease. The quoted sentences say what the papers report.
hepatocellular carcinoma (10 papers, 2014 to 2025). A malignant tumor that arises from hepatocytes. "For example, miR-26b-5p is reported as a potent inhibitor of the nuclear factor kappa-B (NF-κB) pathway by targeting TGF-beta activated kinase 1 (TAK1) and TGF-beta activated kinase 1 binding protein 3 (TAB3) in hepatocellular carcinoma." (PMID 36737782, 2023). "Recently, it was reported that miR-195 inhibited cell survival, migration and invasion by targeting TAB3 expression in hepatocellular carcinoma." (PMID 27009840, 2016). "Conversely, TAB3 was reported to be upregulated in hepatocellular carcinoma and colorectal cancer." (PMID 41332473, 2025). "Additionally, miR-195 reduces the expression of multiple NF-κB downstream effectors by directly targeting IKKα and TAB3 in hepatocellular carcinoma (HCC) and inhibits an M1-like polarization-induced proinflammatory profile in macrophages." (PMID 32819407, 2020). "On the contrary, IL-17A inhibited autophagy via TAB2/TAB3-p38 mitogen-activated protein kinase pathways and mTOR signaling in Hepatocellular carcinoma (HCC) cells and keratinocytes." (PMID 31921197, 2019). "Several reports showed TAB3 is markedly overexpressed in various tumor tissues, such as the testis, skin, non-small cell lung cancer (NSCLC), hepatocellular carcinoma (HCC) and small intestinal cancers." (PMID 34012913, 2021). "Some reports have suggested that miR-26b can suppress NF-κB signaling and thereby sensitize hepatocellular carcinoma cells to the doxorubicin-induced apoptosis by inhibiting the expression of TAK1 and TAB3." (PMID 26204489, 2015). "Moreover, FAT10 limits the efficacy of anti-VEGF therapy for hepatocellular carcinoma by simultaneously stabilising multiple proteins, including HIF1α, β-catenin, STAT3, and TAB3 proteins." (PMID 40374601, 2025). "Our findings suggest that miR-26b may also suppress NF-κB signaling and enhance the chemosensitivity of hepatocellular carcinoma cells by targeting TAK1 and TAB3." (PMID 24565101, 2014). "TAB3 is markedly overexpressed in various tumor tissues, such as the testis, skin, non-small cell lung cancer (NSCLC), hepatocellular carcinoma (HCC) and small intestinal cancers." (PMID 29290971, 2017).
triple-negative breast carcinoma (7 papers, 2016 to 2024). An invasive breast carcinoma which is negative for expression of estrogen receptor (ER), progesterone receptor (PR), and human epidermal growth factor receptor 2 (HER2). "Tao and colleagues revealed that the TAK1 binding protein 3 (TAB3) was O-GlcNAcylated at Ser408 in triple negative breast cancer (TNBC), which was required for its Thr404 phosphorylation." (PMID 35432358, 2022). "Another study found that TAB3 was specifically expressed in triple-negative breast cancer, and it was significantly correlated with a poor prognosis in the patients." (PMID 29290971, 2017). "Overexpression of OGT significantly enhances O-GlcNAcylation in TAK1 binding protein 3 (TAB3), promoting migration and invasion of triple-negative breast cancer (TNBC) cells in vivo and in vitro." (PMID 39285476, 2024). "In Axis 2, miR-27b-3p↓TAB3↑, over-expression of TAB3 has been found to promote tumor progression in NSCLC, colorectal cancer, and triple-negative breast cancer." (PMID 34805186, 2021). "Alternatively, it has been demonstrated that O-GlcNAcylation of TAB3 at Ser408 was promoted in triple-negative breast cancer (TNBC) cells, and O-GlcNAcylation levels of TAB3 at Ser408 correlated well with the prognosis of TNBC patients." (PMID 28106845, 2017).
colorectal cancer (4 papers, 2017 to 2025). A primary or metastatic malignant neoplasm that affects the colon or rectum. "In this study, we demonstrated that TAB3 is upregulated in colorectal cancer tissues and that high TAB3 levels correlated with tumor metastasis and a poor prognosis in colorectal cancer." (PMID 29290971, 2017). "In addition, TAB3 knockdown decreased Survivin expression and suppressed colorectal cancer cell migration and invasion in vitro, and reduced liver metastasis in vivo." (PMID 29290971, 2017). "Transforming growth factor-β-activated kinase 1 (TAK1)-binding protein 3 (TAB3) is involved in cancer proliferation and metastasis, but its role in colorectal cancer remains unclear." (PMID 29290971, 2017). "For instance, ZEB2-AS1 could enhance epithelial-mesenchymal transition through the miR-1205/CRKL pathway in colorectal cancer and may be involved in the occurrence and development of colon cancer by regulating the glycolysis process through the miR-188/TAB3 pathway." (PMID 36420274, 2022).
atherosclerosis (3 papers, 2014 to 2024). A disease characterized by the build-up of fatty material and calcium deposition in the arterial wall resulting in partial or complete occlusion of the arterial lumen. "miR-487a may be involved in the occurrence of atherosclerosis by regulating TAB3 expression." (PMID 31011482, 2019).
breast carcinoma (3 papers, 2016 to 2022). "We found that TAB3 and TAB3 O-GlcNAcylation immunoreactivity were identified only in the ER-PR-HER2- TNBC cases of breast cancer, but rarely in ER+PR+ lumina subtype or HER2+ patients, which was similar to the finding in cells." (PMID 27009840, 2016). "TAB3 O-GlcNAcylation promotes breast cancer metastasis by activating NF-κB signal transduction." (PMID 27009840, 2016). "To identify whether TAB3 was O-GlcNAcylated in breast cancer cells, we used several approaches to detect its O-GlcNAc modification." (PMID 27009840, 2016). "Previous studies have demonstrated TAB3 promote breast cancer metastasis." (PMID 27009840, 2016). "Therefore, we focused on the role of TAB3 O-GlcNAcylation in breast cancer." (PMID 27009840, 2016). "However, whether TAB3 is involved in breast cancer metastasis is enigmatic." (PMID 27009840, 2016). "Since TAB1 is not expressed and TAB2 in not O-GlcNAcylated in breast cancer by our previous results, the present study focus on whether TAB3 O-GlcNAcylationis participating in the metastasis of breast cancer." (PMID 27009840, 2016).
arteriosclerosis (1 paper, 2014). A vascular disorder characterized by thickening and hardening of the walls of the arteries. "TGF-β has been found to be an atheroprotective factor in arteriosclerosis, and the TGF-β/Smad pathway can suppress NF-kB activation-induced inflammation by blocking TAB2 or TAB3." (PMID 25198728, 2014).
esophageal squamous cell carcinoma (1 paper, 2021). Esophageal squamous cell carcinoma (ESCC) is a type of esophageal carcinoma (EC) that can affect any part of the esophagus, but is usually located in the upper or middle third. "TAB3 gene overexpression is associated with poor survival in human esophageal squamous cell carcinoma." (PMID 33521362, 2021).
ischemia (1 paper, 2023). A hypoperfusion of the BLOOD through an organ or tissue caused by a PATHOLOGIC CONSTRICTION or obstruction of its BLOOD VESSELS, or an absence of BLOOD CIRCULATION. "The up regulation of miR-23b decreses TAB3 and NF-κB expressions in the hippocampus in ischemia reperfusion rats and preserved the neurons against neuronal death caused by acute ischemia reperfusion damage." (PMID 37727513, 2023).
nasopharyngeal carcinoma (1 paper, 2023). A carcinoma arising from the nasopharyngeal epithelium. "In nasopharyngeal carcinoma, EBV-infection-induced GPX4 combined with TAK1–TAB1/TAB3 complex activated NFκB signaling pathway." (PMID 37268653, 2023).
nephritis (1 paper, 2024). Inflammation of renal tissue. "For example, METTL3 increased the m6A modification of TAB3 and promoted the stability of TAB3 in an IGF2BP2-dependent mechanism, leading to the development of nephritis." (PMID 39337381, 2024).
pneumonia (1 paper, 2023). An acute, acute and chronic, or chronic inflammation focally or diffusely affecting the lung parenchyma, caused by an infection in one or both of the lungs (by bacteria, viruses, fungi, or mycoplasma.). "In contrast, gp78 could bind to TAB3 to promote TAK1 activation, promoting the progression of pneumonia." (PMID 38065978, 2023).
small intestinal cancers (1 paper, 2014). "TAB3 is markedly overexpressed in skin, testis and small intestinal cancers." (PMID 24565101, 2014).
virus infection (1 paper, 2016). "As the key modulator of NF-κB, TAB3 played an essential role in immunity, such as anti-virus infection, B cell activation and endotoxin shock." (PMID 27009840, 2016).
tumor (15 papers, 2013 to 2024). "Taken together, Lnc-PCIR as the oncogenic driver in TNBC, they make a meaningful contribution to tumor progression through activating the NF-κB signaling by associated with TAB3." (PMID 34012913, 2021). "In this study, we first demonstrated that TAB3 is upregulated in CRC tissues compared with non-tumor tissues and that the overexpression of TAB3 is associated with metastasis and poor survival of CRC patients." (PMID 29290971, 2017). "By targeting TAB3, hsa-miR-27b acted as a tumour suppressor by inactivating the NF-кB pathway in HCC in vitro and in vivo, indicating its therapeutic value against HCC." (PMID 36138344, 2022). "IHC analysis of subcutaneous tumour sections from nude mice showed that the expression level of TAB3 increased in the hsa-miR-27b knockdown group and decreased in the hsa-miR-27b overexpression group." (PMID 36138344, 2022). "Several reports demonstrated TAB3 is widely expressed and constitutively overexpressed in certain tumor tissues, which as the oncogene to driving the occurrence and development of tumors." (PMID 34012913, 2021). "Our findings suggest that Lnc-PCIR promotes tumor growth and metastasis via up-regulating the mRNA/protein level of TAB3 and PABPC4, activating TNF-α/NF-κB signaling pathway in TNBC." (PMID 34012913, 2021). "MAP3K7 requires TAK1-binding protein 1 (TAB1), TAB2, and TAB3 to trigger NF-κB activation, which is a key transcription factor for tumor initiation and malignancy." (PMID 31214512, 2019). "To verify the specificity of this tumor-promoting effect, we developed stable clones with TAB3 overexpression from HCT-116 and DLD-1 cells." (PMID 29290971, 2017). "In the 120 TNBC samples, the expression of TAB3 and its O-GlcNAc modification were associated with the tumor grade and the lymph nodes metastases, but was no associated with patients' age and tumor size." (PMID 27009840, 2016). "miR-195 may exert its tumor suppressive function by decreasing the expression of multiple NF-κB downstream effectors by way of the direct targeting of IKKα and TAB3 in HCC." (PMID 26231037, 2015). "miR-195 may also exert its tumor suppressive effects by decreasing the expression of multiple NF-κB downstream effectors via direct targeting of IKKα and TAB3." (PMID 24205035, 2013). "The expression of TAB3 in tumours was significantly higher than that in non-tumourous liver tissue, as shown by western blot." (PMID 36138344, 2022). "First, miR-195-5p has been found to suppress tumor by decreasing the expression of multiple NF-κB downstream effectors by directly targeting nuclear factor kappa-B kinase subunit alpha (IKK α) and transforming growth factor-beta(TGF-β)-activated kinase 1 and MAP3K7-binding protein 3 (TAB3)." (PMID 34221706, 2021). "Moreover, miR-195 exerted its tumor suppressive effect by targeting VEGF, IKKα, and TAB3 in HCC." (PMID 28740507, 2017).
cancer (10 papers, 2014 to 2024). A tumor composed of atypical neoplastic, often pleomorphic cells that invade other tissues. "TAB3 is involved in regulating differentiation and progression in several cancer types by modulating NF-кB signalling." (PMID 36138344, 2022). "TAB3 is dysregulated in a variety of cancers and participates in the activation of the NF-кB pathway." (PMID 36138344, 2022). "Recent emerging evidence has indicated that TAB3 also plays a crucial role in cancer development and chemoresistance." (PMID 29290971, 2017). "Our findings provide insight into the regulatory mechanism of TAB3 function and reveal the implication of aberrant TAB3 O-GlcNAcylation in cancer metastasis." (PMID 27009840, 2016). "In further, TAB3 O-GlcNAcylation was essential in cancer metastasis both in vivo and in vitro." (PMID 27009840, 2016). "We found that miR-26b suppressed the TNFα- and doxorubicin-activated NF-κB signaling in HCC cells, and sensitized cancer cells to the doxorubicin-induced apoptosis by targeting TAK1 and TAB3." (PMID 24565101, 2014). "While other TAB partners of TAK1, namely TAB2 or TAB3, may be involved in the regulation of TAK1 activity in other chronic conditions such as cancer, our focus remains on TAK1/TAB1 complex given its established role in IL-1β-induced TAK1 activation in human RASFs." (PMID 36032089, 2022).
TAB3 also shares sentences with these, for which no sentence is quoted: acute kidney injury (1 paper); autoimmune disease (1); colon cancer (1); COVID-19 (1); E. Coli infection (1); helminth infections (1); metastatic colorectal cancer (1); non-small cell lung carcinoma (1); renal fibrosis (1); Ureteral obstruction (1).